XAGE2 (X antigen family member 2)
Synonyms: XAGE-2; CT12.2; GAGED3; XAGE2B
Tractability: Antibody: the Human Protein Atlas places it where antibodies can reach.
Gene: Protein-coding gene on chromosome X (52,368,577 to 52,375,680, forward strand). Ensembl gene ENSG00000155622.
Subcellular location (Human Protein Atlas): Vesicles; Plasma membrane
Gene Ontology:
Molecular function: protein binding
Homologues: Orthologues: chimpanzee XAGE2 (98% identical), macaque XAGE2 (86% identical). Paralogues in human: XAGE3 (72% identical), XAGE5 (68% identical), GAGE10 (49% identical), GAGE1 (48% identical), GAGE12H (47% identical), GAGE12C (46% identical), GAGE12D (46% identical), GAGE12E (46% identical), GAGE12F (46% identical), GAGE12G (46% identical), GAGE12J (46% identical), GAGE13 (46% identical), and 10 more.
Diseases named in the same sentence as XAGE2 in open-access papers:
XAGE2 is named in the same sentence as 4 diseases in open-access papers, as found by Europe PMC text mining. Sharing a sentence is not in itself a finding about the gene and the disease. The quoted sentences say what the papers report.
tumor (1 paper, 2013). "XAGE2 is strongly expressed in normal testes, and in some tumor." (PMID 23613972, 2013).
XAGE2 also shares sentences with these, for which no sentence is quoted: cancer (1 paper); carcinosarcoma (1); melanoma (1).